CD4 (CD4 molecule)
Diseases named in the same sentence as CD4 in open-access papers (continued):
Sharing a sentence is not in itself a finding about the gene and the disease.
sarcoidosis (continued). "Activated T helper (Th)-1 pulmonary CD4+ cells and their mediators are essential for the inflammation and granulomatous process in sarcoidosis." (PMID 19480659, 2009). "Sarcoidosis is associated with an increase in the number of alveolar T cells (CD3+ cells) and an increase of the CD3+CD4+ lymphocyte subset." (PMID 19242869, 2009). "We have found previously a significant decrease of BAL fluid CD4/CD8 ratio with increasing radiographic stage of sarcoidosis." (PMID 19242869, 2009). "In the current study we examined the mRNA expression of TIM-1 and TIM-3 as well as Th1 and Th2 cytokines in CD4+ T cells sorted by means of flow cytometry from BALF of patients with active sarcoidosis and healthy subjects." (PMID 19480659, 2009). "There was a significant increase in the relative expression of IL-2 mRNA in CD4+ T cells from sarcoidosis patients compared with controls (p = 0.008)." (PMID 19480659, 2009). "We demonstrate here a decreased mRNA and protein expression of TIM-3 in the BALF CD4+ T cells of sarcoidosis patients versus controls and decreased mRNA expression of TIM-1 in non-Löfgren's patiens versus Löfgren's patients." (PMID 19480659, 2009). "Significant BAL fluid lymphocytosis and increased CD4/CD8 ratio were characteristic for all three sarcoidosis patient groups." (PMID 19242869, 2009). "When investigating associations between TIM molecules and BALF cellular parameters in patients, TIM-3 mRNA levels correlated negatively with the ratio of CD4+ to the CD8+ T cells in the lungs of sarcoidosis patients (r = -0.4, p = 0.035)." (PMID 19480659, 2009). "Sarcoidosis is a Th1-mediated disease with accumulated CD4+ T cells in the lungs resulting in an increased BALF CD4+ to CD8+ T cell ratio, which has become a clinically important marker of sarcoidosis." (PMID 19480659, 2009). "Additional studies have revealed a strong association between HLA-DRB1*0301 and remarkable expansions of CD4+ T cells expressing T-cell receptors using the AV2S3 gene segment in bronchoalveolar lavage fluid (BALF) of Scandinavian sarcoidosis patients." (PMID 19480659, 2009). "The increase in BAL lymphocytes and the CD4/CD8 ratio of BAL lymphocytes is a typical feature of sarcoidosis." (PMID 19242869, 2009). "In this study, we demonstrate a decreased mRNA and protein level of TIM-3 in BALF CD4+ T cells of sarcoidosis patients with active disease, while IL-2 mRNA expression was elevated." (PMID 19480659, 2009). "Macrophages, bearing increased expression of major histocompatibility class (MHC) II molecules, most likely initiate the inflammatory response of sarcoidosis by presenting an unidentified antigen to CD4+ Th (helper-inducer) lymphocytes." (PMID 18811966, 2008). "Macrophages bearing an increased expression of major histocompatibility class (MHC) II molecules most likely initiate the inflammatory response of sarcoidosis by presenting an unidentified antigen to CD4+ Th (helper-inducer) lymphocytes." (PMID 18811966, 2008). "In BALF the percentage of IFN-γ producing CD4+ Tcells was significantly higher in patients with sarcoidosis than in normal control subjects (mean ± SD, 53.1 ± 17.9 versus 38.1 ± + 7.7, p = 0.019) after the stimulation with PMA/ionomycin." (PMID 15978129, 2005). "Based on our findings that there is a positive correlation between BALF and induced sputum lymphocyte counts (r = 0.616) and CD4+/CD8+ ratio (r = 0.7) we aimed to evaluate the Th1/Th2 balance in sarcoidosis in both BALF and induced sputum." (PMID 15978129, 2005). "In induced sputum the percentage of IFN-γ producing CD4+ T cells was significantly higher in patients with sarcoidosis than in normal control subjects (mean ± SD, 60.0 ± 23.3 versus 35.60 ± 12.46, p = 0.003) after the stimulation." (PMID 15978129, 2005). "Sarcoidosis patients had an increased number of CD4+ -IFN-γ producing cells in IS (p = 0.003) and BALF (p = 0.01) in comparison with normal subjects." (PMID 15978129, 2005).
sarcoidosis (continued). "The proposed pathogenesis of sarcoidosis involves and exaggerated immune response to an unknown antigen, leading to the activation and accumulation of T-Lymphocytes, especially CD4+ T cells, macrophages and granuloma formation in affected tissues." (PMID 41523467, 2025). "Thus, at the tissue level, sarcoidosis-like disease is characterised by an immune reaction that induces granulomas with epithelioid cells surrounded by a ring of CD4+ and CD8+ T lymphocytes." (PMID 40943893, 2025). "The ratio of CD4/CD8 being increased in sarcoidosis was previously reported." (PMID 40725075, 2025). "The role of other inflammatory cells in sarcoidosis immunopathogenesis is under intensive research, including natural killer (NK) cells and B cells, with studies suggesting possible interplays between their function and CD4+ T cells." (PMID 40002701, 2025). "In the present work, an increased pulmonary CD4/CD8 ratio was associated with earlier onset of respiratory distress from thoracic radiation exposure in mice, as has been reported in the clinical lung response of sarcoidosis." (PMID 41261392, 2025). "CD4+ T helper cells play a central role in the pathogenesis of sarcoidosis." (PMID 40002701, 2025). "T CD4 lymphocytes remain key players in the pathogenesis of sarcoidosis." (PMID 40217830, 2025). "Genome-wide association studies (GWAS) in sarcoidosis have identified multiple susceptibility loci, particularly within the HLA class II region including HLA-DRB1, DQA1, and DQB1, implicating antigen presentation to CD4+T cells in pathogenesis." (PMID 41197661, 2025). "Scholarly investigations have further revealed a decrease in peripheral blood CD4+ T and CD8+ T lymphocytes in individuals afflicted with pulmonary sarcoidosis, which is directly associated with the severity of sarcoidosis and the extent of pulmonary function decline." (PMID 40755006, 2025). "Sarcoidosis belongs to the group of granulomatous lung diseases and is characterized by the formation of noncaseous granulomas represented by a conglomerate of epithelioid and multinucleated cells surrounded by CD4+, CD8+ T-lymphocytes and B-lymphocytes." (PMID 39410592, 2024). "Next, we investigated whether expression of surface markers on sarcoidosis CD4+ Tm cells at baseline correlated with the response to prednisone." (PMID 38715030, 2024). "In addition, a significant decrease of FoxP3+CD25+ T-regs among the memory CD4+ T cell compartment has been described, compared to sarcoidosis." (PMID 39062076, 2024). "Increase in CXCR3 CD226 CD4 in sarcoidosis • CXCL9 and CXCL11 are ligands of CXCR3, are IFN-inducible and found in granulomas.• CXCR3 expressing CD4+ T cells are recruited in granuloma.B cells: more prevalent in the BAL of sarcoidosis and CTD-ILD patients compared to IPF." (PMID 39896815, 2024). "Another effector CD4+ T cell, Th17, has also been shown to be important in both TB and sarcoidosis." (PMID 38165044, 2024). "However, for both TB and sarcoidosis, CD4+ T lymphocytes are integral to the granulomatous structure." (PMID 38165044, 2024). "In this study, we hypothesized that the PB CD4+ T cell phenotype of patients with sarcoidosis might correlate with response to prednisone treatment." (PMID 38715030, 2024). "Studies have characterized many different T cell effector lineages which may affect the pathobiology of sarcoidosis including Th1 T cell skewing and IFNγ production in the CD4+ T cell compartment." (PMID 36893197, 2023). "Additionally, among sarcoidosis patients experiencing disease progression, females expressed significantly higher IL-6 levels in their CD4+ T cells compared to males." (PMID 36899902, 2023). "Originally, sarcoidosis was described as a disease driven by CD4+ T cells." (PMID 37239108, 2023). "However, a seminal report implicated PD1+CD4+ T lymphocytes and PD1+Th17 lymphocytes as key drivers of fibrosis via TGF-β1 secretion in idiopathic pulmonary fibrosis and sarcoidosis-associated pulmonary fibrosis." (PMID 37256147, 2023).
sarcoidosis (continued). "The flow cytometric analysis of the proportion of diverse CD4+ T-cell subsets in the blood of sarcoidosis patients showed that Tregs, Th1, Th17, and Th17.1 cells constituted 7.1% ± 0.7%, 3.0% ± 0.3%, 10.25% ± 0.6%, and 3.15% ± 0.3%, of CD4+ T cells, respectively." (PMID 37520566, 2023). "Cluster #5508, prevalent in sarcoidosis, was characterized by CD4+ CD226+ CXCR3+." (PMID 36949950, 2023). "Within PBMC, the CD4+ subset was considerably decreased in sarcoidosis samples." (PMID 38173720, 2023). "We showed increased levels of CXCR3+ CD226+ CD4+ T cells in sarcoidosis." (PMID 36949950, 2023). "In addition, the level of Nf-kB/p65 was also analyzed in CD4+ T cells, and it was seen that even in CD4+ naïve patients with severe sarcoidosis, the levels of this protein are very low." (PMID 37761266, 2023). "In patients with active sarcoidosis, CD4+ T cells accumulate in granulomatous lung tissue." (PMID 37062818, 2023). "Thus, serum CTO activity proves to be as accurate asBAL CD4/ CD8 in the differential diagnosis of sarcoidosis." (PMID 38152007, 2023). "Since IFN-γ and TNF-α production by CD4+ T cells is hardly inhibited by Tregs in active sarcoidosis patients, we considered infliximab treatment as a chance for reducing inflammation, counteracting changes of immune cell frequencies and thereby ameliorating PML." (PMID 34993476, 2022). "This pathway may be correlated with PD-1 manipulation of STAT3 expression in patients with sarcoidosis since a recent study showed that PD- 1 inhibits PI3K expression in CD4+ T cells in sarcoidosis." (PMID 36544757, 2022). "Pathway analysis was performed and indeed IFN-γ was the most highly significant predicted upstream cytokine regulator of Mac SAR-1 clusters based on their transcriptional profile and consistent with the upregulation of IFNG observed in CD4+ T cells in sarcoidosis." (PMID 35668129, 2022). "In sarcoidosis, a multi-systemic granulomatous disease affecting mainly the lungs, alveolar CD4+ T cells present an unknown antigen interacting with HLA class II molecules." (PMID 35661780, 2022). "CINS patients with associated sarcoidosis had overall similar clinical and biological presentation than CINS patients associated with other conditions but exhibited a lower rate of positive blood cryptococcal antigen testing and higher CD4/CD8 T cells ratio." (PMID 35425769, 2022). "In another study, PD-1+ CD4 T-cell levels in blood were higher in patients with active sarcoidosis (defined by reduced FVC, radiographic progression or acceleration of pulmonary symptoms) compared to resolved disease, although IL-17 secretion by these cells was not evaluated." (PMID 36543347, 2022). "A BAL cell pattern with a CD4/CD8 ratio > 3.5 has been postulated as a potential diagnostic indication of sarcoidosis but has not been observed in LLN samples obtained by EBUS-TBNA." (PMID 35629428, 2022). "A feature of sarcoidosis is the accumulation of CD4+ T lymphocytes in the granulomas." (PMID 35629428, 2022). "However, the Tregs exhibited an antiproliferative effect on CD4+ T cells, which were overly active in sarcoidosis patients." (PMID 34993476, 2022). "Upregulation of PD-1 was also present in PB CD4+ T cells of sarcoidosis patients." (PMID 36685602, 2022). "Indeed, a distinct CD4+FOXP3- cluster present exclusively in the sarcoidosis samples, with a Th1 phenotype marked by upregulation of IFNG and to a lesser degree CSF2 (GM-CSF), was identified." (PMID 35668129, 2022). "CINS patients associated with sarcoidosis had overall similar clinical and biological presentation than CINS patients associated with other conditions but exhibited a lower rate of positive blood cryptococcal antigen testing and higher CD4/CD8 T cells ratio." (PMID 35425769, 2022). "Interestingly, despite cohort heterogeneity, CD14+ monocyte and CD4+ T-cell proportions in sarcoidosis cases and controls were comparable between cohorts." (PMID 36311769, 2022).
sarcoidosis (continued). "It has also been reported that the proliferative capacity of CD4+ T cells in peripheral blood of patients with sarcoidosis was decreased, compared with healthy controls, and that proliferative capacity was restored to the level of healthy controls by blockade of the PD-1 pathway." (PMID 34572417, 2021). "CD4/CD8 ratio in BAL fluid was significantly higher in sarcoidosis than in CVID-RGD patients." (PMID 33807303, 2021). "In conclusion, we suggest that sarcoidosis patients should be closely monitored for: (a) the presence of antiphospholipid antibody positivity; (b) any previous venous thromboembolism episodes; and (c) a reduced CD4 and CD8 lymphocyte ratio." (PMID 34199396, 2021). "When lymphocytes subpopulations analysis was available, mean CD4/CD8 ratio (19 patients) was 2.23 (SD 1.93), median was 1.58 (IQ range 0.53–3.6); 5 patients presented a CD4/CD8 ratio >3.5, as per sarcoidosis diagnostic criteria and 7 > 3.0; in 7 patients ratio was reduced (<1.4)." (PMID 33777011, 2021). "It has been reported that the expression of PD-1 on CD4+ T cells in BALF is higher in patients with sarcoidosis than in healthy controls, but it has been uncertain whether differences in PD-1 expression level are associated with changes in imaging findings." (PMID 34572417, 2021). "Although it has been reported that expression of TIM-3 on CD4+ T cells in BALF is lower in patients with sarcoidosis, compared with healthy controls, the relationship between TIM-3 and sarcoidosis remains unclear." (PMID 34572417, 2021). "Previous reports have suggested that PD-1 and TIM-3 expressed on CD4+ T cells in BALF may be involved in the pathogenesis of sarcoidosis." (PMID 34572417, 2021). "Interestingly, CD4+ T-cell counts in both Clusters 2 and 3 were found to be decreased in relation to reference ranges in the healthy population and sarcoidosis." (PMID 33718397, 2021). "Accumulation of CD4+ T lymphocytes and macrophages transforming into epithelial cells and forming granulomas consists of epithelial and giant cells surrounded by lymphocytes and fibroblasts are characteristic features of sarcoidosis." (PMID 34943912, 2021). "Several studies have suggested that the BALF CD4/CD8 ratio may complement the results of other tests when diagnosing sarcoidosis." (PMID 34943912, 2021). "Interestingly, CBD mice displayed increased CD4 : CD8 ratios thereby paralleling the CD4+ T cell lymphocytosis in the BAL of sarcoidosis patients." (PMID 34054347, 2021). "Despite the need for external validation, we conclude that absolute CD4+ T-cell counts, or absolute lymphocyte counts in lieu of CD4+ T-cell enumeration, may serve as a predictor of sarcoidosis inflammatory activity." (PMID 33718397, 2021). "T regulatory cells (Treg), a CD4+ T-cell subset that acts to suppress other immune cells from reacting to self or foreign antigens, were found to be increased in the peripheral blood of sarcoidosis patients but present in normal levels in sarcoid BAL fluid." (PMID 33036432, 2020). "CD4+ T cells from the BAL of sarcoidosis patients are also highly Th1 polarized." (PMID 32256501, 2020). "Although the inciting antigen(s) in sarcoidosis is unknown, there is strong evidence suggesting that the disease is driven by antigen-specific CD4+ T cells in the lungs of patients." (PMID 32256501, 2020). "In an interesting twist, recent studies have shown that TH17 CD4+ T-cells may contribute equally or more to the pathogenesis of sarcoidosis than the traditionally assumed TH1 CD4+ T-cells." (PMID 33036432, 2020). "The ratio of CD4+/CD8+ lymphocytes in BALF is often elevated in patients with sarcoidosis." (PMID 33178707, 2020). "Furthermore, inhaled VIP administered in a clinical trial for sarcoidosis patients was found to significantly increase the numbers of CD4+CD127−CD25+ FOXP3+ T cells in the BAL." (PMID 33176790, 2020).
sarcoidosis (continued). "The other two were patients investigated because of suspicion of sarcoidosis with radiological NSIP, one with unknown cause and one with dermatomyositis, both with low CD4/CD8-ratio of 0.4 and 0.2." (PMID 32111204, 2020). "These collective findings indicate a state of CD4+ T-cell anergy in sarcoidosis." (PMID 33036432, 2020). "Pulmonary CD4+ T cells from sarcoidosis spontaneously secrete IL-2 ex vivo, but when given TCR stimulation, these cells express less IL-2 and IFN-γ relative to CD4+ T cells from various other lung diseases and healthy control subjects, consistent with an anergic/exhausted phenotype." (PMID 32256501, 2020). "However, increased CD4+ Vα2.3+ T-cells in BALF (> 10.5%) is highly specific for sarcoidosis (specificity 97%)." (PMID 32111204, 2020). "Additionally, sarcoidosis CD4+ T cells have a reduced proliferative capacity and higher levels of apoptosis, along with increased PD-1 expression, which is often associated with persistent antigen exposure to limit chronic T cell activation." (PMID 32256501, 2020). "Whether these exposures are driving sarcoidosis by activating specific CD4+ T cells in the lung or are merely inducing an inflammatory environment that makes individuals more susceptible to disease is currently unknown." (PMID 32256501, 2020). "T-cells, particularly activated CD4+ T-cells, play a key role in the inflammation in sarcoidosis." (PMID 32722050, 2020). "A lung accumulation of CD4+ Vα2.3+ T-cells is well known and characteristic for sarcoidosis." (PMID 32111204, 2020). "Therefore, a CD103+CD4+/CD4+ ratio 0.2 can be seen as additional evidence pointing towards a diagnosis of sarcoidosis." (PMID 32760396, 2020). "Pulmonary CD4+ T cells from patients with sarcoidosis spontaneously secrete IL-2 ex vivo, but upon TCR stimulation, they express less IL-2 and IFN-γ compared to CD4+ T cells from other lung diseases and healthy controls, in line with an anergic/exhausted phenotype." (PMID 32722050, 2020). "Taken together, no serological biomarker has so far proven ideal and in this setting we believe that CD4+ Vα2.3+ T-cells could provide additional valuable information in diagnosing and in some cases monitoring sarcoidosis." (PMID 32111204, 2020). "The typically increased CD4/CD8 ratio in sarcoidosis was less frequently seen in CVID patients." (PMID 33613543, 2020). "One study detailed significantly decreased NKT cell frequency in BAL fluid of sarcoidosis patients compared to healthy controls which correlated with increased lymphocytosis of mostly CD4+ T-cells in BAL fluid, suggesting resulting amplification of the adaptive immune response." (PMID 33036432, 2020). "Sarcoidosis is a granulomatous disease of unknown etiology characterized by compartmentalization of CD4 T helper 1 (TH1) cells and activated monocyte/macrophages in the organs involved." (PMID 32728980, 2020). "However, functional differences were observed in CD4+CD25high cells from healthy subjects compared to those of patients with sarcoidosis." (PMID 32751786, 2020). "This suggests that this T-cell subset could be used as an additional tool to the CD4/CD8-ratio to support the sarcoidosis diagnosis, particularly in patients with LS but also in patients with non-LS." (PMID 32111204, 2020). "We suggest therefore that analyzing the proportion of CD4+ Vα2.3+ BAL T-cells in patients with sarcoidosis could be valuable as a complement to the CD4/CD8-ratio." (PMID 32111204, 2020). "Similarly, iPS-RPE cells significantly suppressed IFN-γ production of Th1-type CD4+ uveitis T cells in patients with HLA-B27 associated acute anterior uveitis, acute retinal necrosis, CMV retinitis, sarcoidosis, VKH disease, and Behçet’s disease." (PMID 32899567, 2020).